EZH2 (enhancer of zeste 2 polycomb repressive complex 2 subunit)
Diseases named in the same sentence as EZH2 in open-access papers (continued):
Sharing a sentence is not in itself a finding about the gene and the disease.
breast cancer (continued). "In breast cancer, EZH2-mediated suppression of growth-regulating estrogen receptor binding 1 (GREB1), an ERα cofactor, drives tamoxifen resistance." (PMID 40843360, 2025). "Breast cancer patients with high EZH2, ICOSLG expression and low DPP4 expresssion had potentially stronger ability to release sICOSL, and thus a significant adverse overall survival." (PMID 40708008, 2025). "ZLD1039, a potent and selective inhibitor of EZH2, has demonstrated efficacy in preventing breast cancer and acute kidney disease." (PMID 40478495, 2025). "More recently, we demonstrated that USP30-AS1 is significantly upregulated in breast cancer, particularly in triple-negative subtype, where it promotes tumor proliferation through both the hnRNP-F/P21 and EZH2/c-Myc/p21 axes." (PMID 41614739, 2025). "DEK and EZH2 protein and mRNA expression levels were, indeed, strongly positively correlated in human breast cancers." (PMID 40562540, 2025). "In breast cancer, EZH2 maintains luminal progenitor cells and restricts their differentiation by repressing enhancers of GATA3, a key TF driving luminal cell differentiation." (PMID 40032852, 2025). "ZLD1039 has been reported as a selective inhibitor of EZH2 with anti-tumor effects in breast cancer and renal protective effects." (PMID 40478495, 2025). "Breast cancer cell lines were treated with EZH2i (EZH2 inhibitor) and/or paclitaxel, the cytotoxic drug with the strongest ability to induce sICOSL release." (PMID 40708008, 2025). "Conversely, targeting EZH2 impairs mTORC1 activity through an indirect mechanism that upregulates PTEN expression in breast cancer patients." (PMID 39054369, 2024). "GSK3β also phosphorylates EZH2 on S363, reducing H3K27me3 and attenuating breast cancer oncogenic activity." (PMID 39769907, 2024). "The expression of EZH2 can also be directly correlated with patient survival, as is the case with breast cancer patients with visceral metastasis (VM)." (PMID 39768352, 2024). "High nuclear levels of EZH2 correlate with increased proliferation, indicated by high Ki67 expression, and poor prognosis in melanoma, prostate, endometrial, and breast cancer." (PMID 39409910, 2024). "An early study in breast cancer has shown that O‐GlcNAc at Ser‐75 stabilized EZH2, and facilitated H3K27me3 on target genes." (PMID 38494860, 2024). "A signature performed by four of these hub nodes (CDK1, PCNA, EZH2, and BUB1) was associated with relapse events in untreated luminal breast cancer patients." (PMID 38831458, 2024). "Studies provide evidence of elevated EZH2 expression in various cancer types, such as breast cancer, glioblastoma, ovarian cancer, gastric cancer, prostate cancer, esophageal cancer, anaplastic thyroid carcinoma, and nasopharyngeal carcinoma." (PMID 38534385, 2024). "On the other hand, EZH2 silences NF-κB by methylating its promoters in ER-positive luminal-like breast cancer cells, preventing the expression of the NF-kB target gene." (PMID 39767641, 2024). "In breast cancer, Pengnan Hu verified that the cell invasion of breast cancer can be inhibited by NBAT-1 through the suppression of the EZH2-induced H3K27me3 of DDK1 mechanically." (PMID 38243168, 2024). "In breast cancer, abnormal expression of EZH2 promotes the growth and invasive ability of cancer cells." (PMID 39072246, 2024). "Previous reports in breast cancer cells have shown that the O‐GlcNAc modification regulates EZH2 protein stability and function." (PMID 38494860, 2024). "Researchers studying a breast cancer cell model have observed a significant inverse relationship between miR-199a/214 expression and the levels of both Ezh2 and Ki-67 proteins." (PMID 38807590, 2024). "For example, AKT-mediated EZH2 phosphorylation reduced EZH2 affinity for histones resulting in a reduction in H3K27me3 levels in breast cancer." (PMID 39561122, 2024). "In agreement, analysis of human patient samples supports that EZH2 is required to efficiently repress mesenchymal genes in breast cancer tumours." (PMID 39174513, 2024).
breast cancer (continued). "We found that EZH2 represses a large set of mesenchymal genes and promotes the residence of breast cancer cells in a more epithelial state." (PMID 39174513, 2024). "The miR-199a/214 cluster has been shown to inhibit the production of Ezh2, β-catenin, or Ki-67, resulting in reduced proliferative activity of breast cancer cells." (PMID 38807590, 2024). "The interaction of TRIM28 with oncogenic EZH2 was also observed, and is found to be critical for EZH2 protein stability and mammosphere formation in breast cancer." (PMID 39451518, 2024). "To analyse the function of EZH2 in breast cancer, we focused on the human MCF-7 cell line because it is a well-established system to study the molecular basis of metastasis in breast adenocarcinomas." (PMID 39174513, 2024). "miR-600 has the capability to impede the malignant behavior of breast cancer cells and enhance their sensitivity to sorafenib through the EZH2/RUNX3 axis." (PMID 38807590, 2024). "Our study reveals that the PRC2 catalytic subunit EZH2 coordinates the repression of the mesenchymal gene expression programme in breast cancer cells, facilitating MET upon TGF-β stimulation decay." (PMID 39174513, 2024). "The tumour‐promoting properties of EZH2 have been demonstrated in various cancers, like ovarian, prostate and breast cancers." (PMID 38652219, 2024). "Both EZH2 and integrin α11 were found to be strong prognostic factors of relapse-free and overall survival of patients with breast cancer, but integrin α11 was a more effective therapeutic target than EZH2 for the treatment of drug-resistant breast cancer." (PMID 38664825, 2024). "In colon cancer, hepatocellular carcinoma, precancerous mammary epithelial lesions, and breast cancer cells, EZH2 binds to β-catenin and activates Wnt signaling." (PMID 38886296, 2024). "The fraction of cells expressing EZH2 in breast cancer LNM was significantly higher than its primary tumor, while E-cadherin expression in the LNM was lower." (PMID 40135141, 2024). "This inhibitor targets the 5’ domain responsible for interaction with EZH2, resulting in the inhibition of metastasis in an orthotopic breast cancer model using cell lines." (PMID 39273054, 2024). "HIF-1α inhibits Rad51 and induces DNA breaks in early-stage breast cancer cells, notably in breast tumor-initiating cells (BTICs) by targeting EZH2." (PMID 38911968, 2024). "In breast cancer tissue, low EZH2-expression supports cell invasion and tumor growth and is correlated with a poor prognosis." (PMID 40135141, 2024). "Overall, we concluded that H3K27me3 deposition through EZH2 is required to maintain the transcriptional repression of mesenchymal genes and favour the residence of breast carcinoma cells in an epithelial state." (PMID 39174513, 2024). "In particular, a study already has found that the formation of CCF in breast cancer cells is correlated to the overexpression of EZH2 and promotes breast cancer metastasis through the secretion of inflammatory factors by the cGAS-STING pathway." (PMID 37543653, 2023). "Data shows that EZH2 expression mRNA level in pan-cancer including breast cancer tissue is higher than the corresponding normal tissue in TCGA dataset." (PMID 37803297, 2023). "Conversely, the methylation of EZH2 at K307 enhanced the H3K27me3-dependent repression of tumour-suppressor genes, promoting breast cancer cell proliferation and invasion." (PMID 37710230, 2023). "To determine EZH2 expression in metastatic breast cancer, we make comparison of EZH2 in each breast cancer N stage group (N0:516 cases, N1:362cases, N2:120cases, N3:77cases) with normal mammary gland tissue (n = 114 cases) based on TCGA database." (PMID 37803297, 2023). "It was demonstrated that p38-induced phosphorylation of EZH2 at Tyr367 promoted its cytoplasmic retention in breast cancer cells." (PMID 37491334, 2023). "For instance, in breast cancer, the enhancer of zeste homolog 2 (EZH2) intensifies FAK/TGF-β signaling, resulting in bone metastasis." (PMID 37174083, 2023).
breast cancer (continued). "Along the same line, the treatment of breast cancer cells with EZH2 inhibitors promotes recruitment and favors M2 polarized macrophage activation by inducing CCL2 upregulation." (PMID 36900330, 2023). "We observed TAK-981 decreased EZH2 level in MM cells, consistent with our findings in colorectal cancer and breast cancer." (PMID 35338347, 2023). "We recently demonstrated that EZH2 is closely linked to the formation of CCF and metastasis in breast cancer." (PMID 37543653, 2023). "This is consistent with the findings of EZH2 in a variety of other tumors, including liver, lung and breast cancer." (PMID 37198697, 2023). "Accordingly, we observed an increased EZH2 phosphorylation levels of T487 and S21 site in breast cancer tissues." (PMID 37803297, 2023). "This process translates into a decreased sensitivity of ER+ breast cancer cells to endocrine therapy, which involves an enhancer of zeste homolog 2 (EZH2)-mediated reprogramming that also seems to induce stemness in breast cancer bone metastasis." (PMID 37182144, 2023). "Afterward, up-regulation of EZH2 was also detected in endometrial carcinoma, anaplastic thyroid carcinoma, esophageal cancer, nasopharyngeal carcinoma, breast cancer, and gastric cancer (GC)." (PMID 36545914, 2023). "We tested a panel of DNA methyltransferase (DNMT) inhibitors, histone deacetylase (HDAC) inhibitors, and EZH2 inhibitors in 6 breast cancer cell lines." (PMID 37567892, 2023). "It has been reported that decreased expression of BRCA1 triggers genome-wide EZH2 retargeting and elevates H3K27me3 levels which blocks embryonic cell differentiation and enhances breast cancer migration and invasion." (PMID 37325482, 2023). "In breast cancer, EZH2 was identified as a regulator of ERRγ activities in a methyltransferase-dependent manner." (PMID 36901694, 2023). "In particular, it has already been suggested that EZH2 promotes the formation of CCFs in breast cancer cells and promotes breast cancer metastasis through the activation of the cGAS-STING pathway by CCFs." (PMID 37543653, 2023). "Meanwhile, CDK2-mediated EZH2 phosphorylation(pT416) drives tumorigenesis— converts the luminal breast cancer to TNBC." (PMID 37803297, 2023). "Accumulating evidence from in vitro and in vivo models together with clinical studies collectively suggests that EZH2 is upregulated in various malignant solid tumors such as lung, hepatocellular, ovarian, colorectal and breast cancers." (PMID 37941056, 2023). "In highly metastatic breast cancer cell lines, an analogous subset is described demonstrating delayed class II upregulation following IFNγ exposure, mediated by IFNγ-induced EZH2 occupancy at CIITA." (PMID 37565053, 2023). "The EZH2 expression has been found to be altered in multiple cancers, such as breast cancer, esophageal cancer, liver cancer and so on." (PMID 36318256, 2023). "For example, in breast cancer, DZNep reduces EZH2 protein stability by upregulating the E3 ligase PRAJA1, and MS1943 depletes EZH2 and induces cytotoxicity." (PMID 36906655, 2023). "We demonstrated for the first time that EZH2 is distributed both in cytoplasm and nucleus of breast cancer cells in a phosphorylation site-specific manner." (PMID 37803297, 2023). "EZH2 directly interacts with other proteins such as breast cancer gene 1 (BRCA1) binding to EZH2 in breast cancer cells." (PMID 37325482, 2023). "In comparison to an epigenetic repressor of tumor-related genes in nucleus, little is known about the function of cytoplasmic EZH2 in tumor cells, breast cancer cells particularly." (PMID 37803297, 2023). "EZH2 expression is amplified in lymphoma, lung cancer, prostate cancer, breast cancer, colon cancer, melanoma, retinoblastoma, and glioblastoma, and EZH2 is involved in the metastasis of prostate and breast cancers." (PMID 38036730, 2023). "EZH2 and JMJD6 gene profiles overlap in breast cancers, with EZH2 co-regulating a unique gene box in both ER+ and ER− cells." (PMID 37069494, 2023).
breast cancer (continued). "EZH2 has also been found to enhance the stemness and metastatic ability of breast cancer, facilitating metastasis from bone to distant organs." (PMID 38041134, 2023). "The experiments conducted in SK-BR-3 and MCF-7 cells showed significant upregulation of an oncogene EZH2, which promotes carcinogenesis and is related to poor prognosis and aggressiveness of breast cancer." (PMID 38132441, 2023). "Taken together, our findings demonstrate for the first time that the expression and subcellular localization of phosphorylated EZH2 differs HER2-positive breast cancer invasiveness in a site-specific manner, suggesting a correlation with lymph node metastasis." (PMID 37803297, 2023). "LncRNA MEG3 regulates chondrogenic differentiation by inhibiting TRIB2, which is achieved by binding with EZH2 as well as LINC02273; it is associated with hnRNPL, which promotes metastasis of breast cancer by increasing AGR2 transcription." (PMID 38017487, 2023). "A large number of studies have indicated that the expression of EZH2 in cancer tissues is abnormally higher than that in normal tissues in a variety of cancers, such as pancreatic, prostate and breast cancer." (PMID 37198697, 2023). "More specifically, we employed a highly aggressive breast cancer cell line (BT549) treated with EZH2 inhibitor (Dznep) for RNA sequencing assays, attempting to identify its downstream target genes in BC in vitro." (PMID 37803297, 2023). "EZH2 is often elevated in breast carcinoma and excessive EZH2 expression facilitates invasive tumor growth and aggressive clinical behavior." (PMID 38268926, 2023). "In breast cancer, EZH2 promotes the expression of nuclear factor-κB (NF-κB) targets and tumor cell growth independent of its histone methyltransferase activity." (PMID 36471782, 2022). "Our data show that EZH2 can promote CCF formation, and EZH2 activates the cGAS–STING pathway through CCF to promote breast cancer metastasis." (PMID 35163710, 2022). "Taken together, this study reveals a potential explanation behind the frustrating results of EZH2 inhibitor EPZ-6438 against breast cancer and sheds light on a translatable and feasible combinational strategy to overcome it." (PMID 36038549, 2022). "EZH2‐mediated up‐ and downregulation of various genes increases cell proliferation, invasion, and metastasis and decreases the apoptosis of breast cancers." (PMID 36188615, 2022). "EZH2 mutations and overexpression of core PRC2 subunits have been found in multiple solid cancers, including prostate and breast cancer, as well as in hematological malignancies." (PMID 36105358, 2022). "Because CCF can activate cGAS, we next investigated if EZH2 can promote breast cancer cell migration and invasion through CCF." (PMID 35163710, 2022). "SOX5 can positively modulate the expression of enhancer of zeste homologue 2 (EZH2) in the context of breast cancer." (PMID 35468879, 2022). "Focusing on breast cancer, EZH2 was found to regulate the structure of basal-like cell populations by inducing a ‘bi-lineage’ differentiation state." (PMID 35955891, 2022). "More importantly, EZH2 has been reported to suppress miR-381 expression to contribute to cisplatin resistance in breast cancer in an epigenetic manner." (PMID 35184652, 2022). "For example, in breast cancer cells, free EZH2 can directly bind the promoter of NOTCH1 to increase NOTCH1 expression." (PMID 36552722, 2022). "It was also reported that the enhancer of zeste homolog 2(EZH2) in breast cancer cells represses the transcription of miR-29b and miR-30d by catalyzing H3K27me3, thereby promoting the expression of LOXL4." (PMID 36293126, 2022). "For bone metastasis outgrowth model, GFP- and luciferase-labeled MDA-MB-231 cells, which have relatively high EZH2 expression among tested breast cancer cell lines, were intratibially injected into nude mice." (PMID 35538070, 2022).
breast cancer (continued). "In the present study, we found that EZH2 upregulated ITGB1 transcription in breast cancer cells by functioning as a transcriptional co-factor of RNA Pol II to facilitate its binding to the ITGB1 promoter." (PMID 35538070, 2022). "Overall, we find that the EZH2-integrin β1-FAK axis cooperates with the TGFβ signaling pathway to promote bone metastasis of breast cancer." (PMID 35538070, 2022). "The overexpression of EZH2 is related to worse survival in NK/T-cell lymphoma, prostate cancer, breast cancer, cutaneous melanoma, gastric cancer, endometrial cancer, and esophageal squamous cell carcinoma." (PMID 36276954, 2022). "Both GTP and EGCG treatment of breast cancer cells drastically lowered the levels of EZH2 and class I HDAC proteins." (PMID 35327559, 2022). "Since FAK and TGFβ enhances epithelial–mesenchymal transition and cell migration, EZH2-induced FAK/TGFβ signaling activation is also an underlying mechanism of the strong migration and invasion ability of EZH2 high expressing breast cancer cells." (PMID 35538070, 2022). "This combination synergistically down-regulates EZH2 expression and inhibit proliferation and migration of breast cancer cells." (PMID 35236381, 2022). "In this study, we elucidate that these epigenetic alterations play a vital role in regulating PDK1 and identify the new regulation axis of EZH2/HDAC2/miR-148a/PDK1 in breast cancer progression and therapeutic resistance." (PMID 35892859, 2022). "We compared the EZH2 level in various breast cancer cells and observed that the EZH2 level in MM-231 and MCF-7/ADR cells were higher than that in MCF-10A and MCF-7 cells." (PMID 35163710, 2022). "This phosphorylation provides the conditions for EZH2 ubiquitination and its subsequent degradation, resulting in a significant decrease in metastasis and migration of breast cancer cells." (PMID 35236381, 2022). "Huang used 83 cancer cell lines derived from hematologic malignancies, breast cancer, liver cancer, pancreatic cancer, and lung cancer, most of which had high levels of EZH2 expression." (PMID 36276954, 2022). "A recent study revealed that P38-mediated EZH2 phosphorylation induced its cytoplasmic localization to promote breast cancer metastasis." (PMID 35085106, 2022). "Among the enzymes implicated in gene regulation via epigenetic mechanisms, the enhancer of zeste homolog 2 (EZH2) is an important histone methyltransferase that methylates H3K27 leading to the transcriptional silencing of the target genes in breast cancer." (PMID 36185256, 2022). "Combined with EZH2 inhibitors and traditional chemotherapy, this will provide new ideas and directions to counter chemotherapy resistance in breast cancer." (PMID 35892859, 2022). "Here we report that EZH2 promotes osteolytic metastasis of breast cancer through regulating transforming growth factor beta (TGFβ) signaling." (PMID 35538070, 2022). "Recent studies revealed that P38-mediated EZH2 T372 phosphorylation induced its cytoplasmic localization to promote breast cancer metastasis." (PMID 35085106, 2022). "This is consistent with the previous finding that Tam resistant breast cancer shows a higher expression of EZH2, a H3K27 methyltransferase, compared to Tam responsive ones." (PMID 35330189, 2022). "We have shown that JMJD6 and EZH2 are almost always co-expressed in breast cancer cells and regulate E2F and DREAM target genes." (PMID 36419768, 2022). "Mounting evidences show that EZH2 is upregulated in multiple malignancies, such as osteosarcoma, breast cancer, melanoma, prostate cancer, and OvCa, and its overexpression is related to the metastatic ability of some aggressive tumors 33-38." (PMID 35154460, 2022). "Since EZH2 knockout significantly inhibited bone metastasis outgrowth, we explored the function of EZH2 in promoting metastatic breast cancer outgrowth in the bone." (PMID 35538070, 2022).